LINC02747 (long independently transcribed non-coding RNA 2747)
Synonyms: AP000439.3; CUPID2; AP000439.2; CUPID1
Gene: Long non-coding RNA gene on chromosome 11 (69,475,567 to 69,481,545, reverse strand). Ensembl gene ENSG00000255774.
Diseases named in the same sentence as LINC02747 in open-access papers:
LINC02747 is named in the same sentence as 5 diseases in open-access papers, as found by Europe PMC text mining. Sharing a sentence is not in itself a finding about the gene and the disease. The quoted sentences say what the papers report.
tumor (2 papers, 2022). "Recently, high LINC02747 expression was significantly associated with advanced tumor TNM stage, histological grade, and poor outcome, thus promoting the proliferation of ccRCC according to inhibit miR-608." (PMID 35242188, 2022).
LINC02747 also shares sentences with these, for which no sentence is quoted: breast carcinoma (3 papers); cancer (2); breast tumors (1); clear cell renal cell carcinoma (1).